METTL3 (methyltransferase 3, N6-adenosine-methyltransferase complex catalytic subunit)
Diseases named in the same sentence as METTL3 in open-access papers (continued):
Sharing a sentence is not in itself a finding about the gene and the disease.
tumor (continued). "To investigate the effects of METTL3 on tumour immunity, we KO the m6A reader Ythdf1‐3 and Mettl3 in B16 cells using CRISPR‐Cas9." (PMID 39568154, 2024). "Studies have shown that METTL3 inhibitors exhibit significant anticancer effects in various tumor models." (PMID 39295872, 2024). "Co-culture experiments with human T cells were performed to evaluate the impact of METTL3 on the enhancement of anti-tumor immunity through in vitro experiments." (PMID 39720723, 2024). "Mechanistically, catalytic inhibition of METTL3 results in dsRNA formation and potent cell‐intrinsic interferon responses that can stimulate anti‐tumour immunity, which is distinct to the mechanism of the current ICBs and cell therapy." (PMID 38545841, 2024). "METTL3-mediated methylation of m6A improves tumor killing by macrophages by enhancing the ability of TAM to polarize toward M1." (PMID 39033180, 2024). "Although the analysis of this review suggests METTL3 is a risk gene for BC, contrast findings are also found in patients with HR + HER2-BC, which suggest a tumor suppressor role for METTL3." (PMID 38961497, 2024). "The suppression of anti-tumor immunity by METTL3 through the m6A–BHLHE41–CXCL1/CXCR2 axis contributes to tumor immune evasion and progression." (PMID 39759516, 2024). "Lactate-induced histone lactylation can elevate METTL3 expression in tumor-infiltrating myeloid cells (TIMs), activating JAK/STAT signaling pathways, thereby fostering an immune-suppressive TME and promoting tumor growth and spread." (PMID 39119332, 2024). "Comparing with monotherapy, a combination of STM2457 and PTX or CBP exhibited more potent in vitro and in vivo anti-tumor efficacy, indicating that targeting METTL3 enhances the sensitivity of NSCLC cells to anticancer agents such as PTX and CBP." (PMID 39309428, 2024). "In clinical applications, although studies have incorporated METTL3 into tumor biomarkers and inhibitor development with great potential, they remain in the early stages and require continued attention." (PMID 38166703, 2024). "METTL3, a key regulator of N6-adenosine methylation (m6A), is associated with the HPV status and expression in tumours and is correlated with a poor prognosis." (PMID 39735605, 2024). "METTL3 was extensively reported as an oncoprotein; therefore, METTL3 inhibitors have the potential to be anti‐tumour drugs." (PMID 38545841, 2024). "In the NAFLD-HCC mouse model, the knockout of METTL3 in conjunction with anti-PD-1 therapy synergistically suppressed tumor growth, resulting in a reduction of over 90% in both tumor volume and weight." (PMID 39372415, 2024). "Subsequently, we validated the expression levels of METTL3 mRNA in 92 pairs of tumor and adjacent normal tissues." (PMID 39497721, 2024). "Studies have shown that knocking out METTL3 or applying METTL3 inhibitors in tumour cells can improve the efficacy of ICB therapy." (PMID 39568154, 2024). "Increasing estrogen receptor-γ levels by promoting METTL3 expression can accelerate fatty acid oxidation and metabolic reprogramming, thereby affecting tumor progression and chemoresistance." (PMID 39033180, 2024). "Further, they found that the knockdown of AKR1B10 reversed the tumor-promoting effects induced by METTL3 overexpression." (PMID 39737179, 2024). "Correlation analysis on 33 tumor types from the TCGA database revealed a strong positive correlation between METTL3 and HMGB1 expression in 31 tumor types, including BLCA." (PMID 38504159, 2024). "In this study, we further confirmed through multi‐data set analysis that the expression of METTL3 was significantly higher in tumour samples than in the control group." (PMID 38429907, 2024). "By designing SAM analogs and conformational inhibitors of METTL3/14, small molecules can downregulate METTL3, thereby reducing m6A levels, and exert anti-tumor effects." (PMID 38711100, 2024). "In the tumor lactoacidotic environment, H3K178ac induces the acetylation and upregulation of METTL3 expression." (PMID 39372415, 2024).
tumor (continued). "Meanwhile, depletion of MDSC by anti-Gr-1 antibody eliminated the tumor-promoting effect of METTL3 in vivo." (PMID 39289775, 2024). "Inhibition of METTL3 not only promotes the immune response and enhances the immunogenicity of tumour cells, but also reverses T‐cell exhaustion in tumour microenvironment, thereby sensitising ICB‐based immunotherapy." (PMID 39568154, 2024). "On the other hand, lactate accumulated in the CRC TME potently induces the upregulation of METTL3 in tumor-infiltrating myeloid cells (TIMs) via the lactylation of histone H3 lysine 18 (H3K18)." (PMID 38322265, 2024). "Taken together, these results suggest that T cells in the STM2457 treated tumour microenvironment undergo significant cell proliferation and activation, indicating that METTL3 inhibition potentiate anti‐PD‐1 therapy by improving T‐cell persistence." (PMID 39568154, 2024). "Experimental validation showed that the expression of these candidate genes was directly regulated through an m6A-dependent mechanism, and inhibition of METTL3 enhances anti-tumor immunity, T cell activation, exhaustion, and infiltration in vitro." (PMID 39720723, 2024). "In clinical settings, METTL3 expression is significantly increased with tumor progression and is positively correlated with PIN1 expression in BC tissues." (PMID 38961497, 2024). "Tumor sphere assay conducted using cells with stably silenced (SCC15-CD44+) or overexpressed (CAL27-CD44+) METTL3 showed that METTL3 upregulation promoted CD44(+) self-renewal potential." (PMID 38355684, 2024). "METTL3, as the writer of m6A, plays a pivotal tumour-suppressor role in PTC carcinogenesis through c-Rel and RelA inactivation of the nuclear factor κB (NF-κB) pathway to regulate tumour growth." (PMID 38993572, 2024). "METTL3 can promote colorectal carcinogenesis by inhibiting anti-tumor immunity through targeting the m6A-BHLHE41-CXCL1 axis." (PMID 39289775, 2024). "METTL3 directly regulates the expression levels of classical oncogenes or tumor suppressor genes, reflecting its important role in tumor progression." (PMID 38798700, 2024). "In thyroid cancer, high expression of METTL3 in tumor cells inhibits the demethylation of CD70mRNA, maintains the degradation of transcripts mediated by YTHDF2, thereby releasing T cells from suppression and enhancing the efficacy of PD-1 blockade." (PMID 39372415, 2024). "Second, METTL3 can promote tumor proliferation by regulating the methylation of various RNAs such as miRNAs, lncRNAs, and circRNAs to affect their expression." (PMID 38711100, 2024). "Lactoacylated METTL3-mediated RNA m6A modification promotes the immunosuppressive inhibition of tumor-infiltrated bone myeloid cells (TIMs), thereby contributing to tumor immune evasion." (PMID 39199429, 2024). "For m6A modification, METTL3 overexpression is associated with poor prognosis in HCC, along with larger tumor size, worse Edmondson–Steiner grade, and advanced tumor stage." (PMID 38566136, 2024). "METTL3-mediated STEAP2 m6A modification plays a tumor suppressive role in PTC by blocking Hedgehog signaling pathway and EMT." (PMID 39403369, 2024). "Knockdown of METTL3 can lead to AS changes in thousands of genes, thereby regulating AS in various tumor cells." (PMID 38405130, 2024). "Growing evidence indicates that METTL3 plays a crucial role in tumorigenesis 25, tumor metastasis 26 and resistance to chemotherapy." (PMID 39309428, 2024). "Results showed that the expression of METTL3 was significantly up-regulated in the tumor tissues of NSCLC." (PMID 38370374, 2024). "METTL3, a key component among methyltransferase enzymes, plays an important role in regulating various tumours." (PMID 38659080, 2024). "In animal experiments, mice inoculated with SUM-1315 cells overexpressing METTL3 exhibited faster tumor growth and higher tumor weight compared to the control group." (PMID 38711100, 2024).
tumor (continued). "We discovered METTL3 inhibition with STM2457 treatment enhances tumour killing by promoting T‐cell function and further improves anti‐PD‐1 therapy in combination of STM2457." (PMID 39568154, 2024). "Preliminary bioinformatics and multi-omics investigations reveal that METTL3’s autonomous role in modulating tumor cell proliferation and its involvement in mRNA splicing are potentially pivotal molecular mechanisms." (PMID 38965238, 2024). "Currently, the role of METTL3 in tumor progression remains contentious, with controversies potentially stemming from variations in cell types, modeling techniques, disease states, or other potential regulatory factors." (PMID 39497721, 2024). "In the realm of tumor metabolism, METTL3 induces m6A methylation of lncRNA ABHD11‐AS1, which enhances the stability of its transcript, resulting in increased expression." (PMID 38706740, 2024). "METTL3 suppresses anti‐tumour immune response by reducing granzyme B and interferon gamma‐positive CD8+ T cell infiltration." (PMID 38545841, 2024). "Functionally, loss and gain studies illustrated that METTL3 promoted the proliferation, invasion, and migration of OSCC cells in vitro and that METTL3 knockdown inhibited tumor growth in vivo." (PMID 38966069, 2024). "The negative feedback-loop regulatory mechanism of METTL3-circMETTL3/ miR-34c-3p-METTL3 promotes TNBC tumor cell proliferation, invasion, metastasis, and growth." (PMID 38961497, 2024). "Our findings suggest that downregulating METTL3 induces alterations in the cellular function and downstream pathways of A549 cells, which are significantly correlated with tumor progression." (PMID 39497721, 2024). "METTL3 serves as the main catalytic subunit of the methyltransferase complex and plays roles in cancer metabolism, either as an oncogene or a tumour suppressor gene." (PMID 39822792, 2024). "HNRNPA2B1 and METTL3, key regulators of m6A modification, play a significant role in immune regulation within the tumor microenvironment." (PMID 38798700, 2024). "The anti‐tumour efficacy of METTL3 inhibition is dependent on an intact immune system, especially T cells." (PMID 39568154, 2024). "Previous studies have shown a positive correlation between the expression level of METTL3 and effector molecules in tumour‐infiltrating NK cells." (PMID 38572667, 2024). "Lactate accumulation in the tumor microenvironment (TME) increases the expression of methyltransferase-like 3 (METTL3) through H3K18la in tumor-infiltrating myeloid cells, enhancing their immunosuppressive functions and promoting immune evasion." (PMID 38993478, 2024). "Research has shown that lactate accumulated in the tumor microenvironment can increase the expression of m6A methyltransferase METTL3 in tumor-infiltrating myeloid cells (TIMs) through H3K18 lactylation." (PMID 39654883, 2024). "We observed that METTL3-KD led to reduced xenografted tumor growth in both ALT+ cell lines, with a more drastic effect in SK-N-FI cells." (PMID 38180812, 2024). "On one hand, METTL3 inhibition enhances the immunogenicity of tumour cells, promoting their recognition by T cells." (PMID 39568154, 2024). "As observed macroscopically, METTL3 KO significantly reduced the number of tumor lesions in the lungs." (PMID 38238831, 2024). "High levels of METTL3 increase the expression of miR221-3p and negatively regulate homeodomain interacting protein kinase 2, a tumor suppressor that can be activated by doxorubicin, thereby reducing the efficacy of doxorubicin." (PMID 39054967, 2024). "Other cancer studies in this area have reported that METTL3 mediates the upregulation of the mRNA levels of tumor angiogenesis-related cytokines and angiogenic factors." (PMID 38166703, 2024). "METTL3‐mediated m6A modification can affect the mRNA expression profile of tumor cells and widely regulate the biological functions of tumors." (PMID 38900084, 2024).
tumor (continued). "METTL3-mediated m6A modification influences NK cell homeostasis and function, affecting tumor growth and survival." (PMID 39512352, 2024). "Tissue slicing also verified that Mettl3–lecKO significantly inhibited lymphangiogenesis in tumor masses." (PMID 39372388, 2024). "METTL3 is also involved in tumor progression of other cancers such as leukemia and bladder and gastric cancers via regulation of their downstream genes." (PMID 39136000, 2024). "Specially, targeting METTL3 in tumour cells can increase the interferon response, enhance MHC‐I exposure, and upregulate PD‐L1 both in vitro and in vivo." (PMID 39568154, 2024). "METTL3 also targets ncRNAs, including pri‐miRNA, to regulate their processing, leading to aberrant expression of their cognate target oncogenes and tumour‐suppressor genes." (PMID 38545841, 2024). "Inhibition of METTL3 suppresses lymphatic vessel growth in both corneal and tumor models, expanding our understanding of its function and highlighting its therapeutic potential." (PMID 39372388, 2024). "The knockdown of METTL3 resulted in decreasing tumour volume, weight, and lymph node metastasis rate in OSCC in vivo." (PMID 39822792, 2024). "Targeting METTL3 enhances anti‐tumour immunity by boosting T‐cell cytotoxicity and reversing T‐cell exhaustion." (PMID 39568154, 2024). "miRNAs are specific transcription factors that regulate METTL3 and can reduce the expression and function of METTL3, thereby altering the tumor-promoting effects of METTL3." (PMID 38166703, 2024). "Experiments confirmed that interfered with METTL3 significantly inhibited glucose uptake and lactate production in tumour cells, and affected the expression of glycolytic‐related genes." (PMID 38429907, 2024). "METTL3 is an essential methyltransferase involved in N6-methyladenosine (m6A) modification and participates in almost all cellular activities 13, including tumor proliferation 14, angiogenesis 15, metastasis 16 and immunity." (PMID 39664566, 2024). "METTL3 is involved in biological processes such as cell differentiation, proliferation, and migration, and it plays a role in many tumor types by mediating RNA m6A modification." (PMID 39195675, 2024). "Our findings demonstrated that overexpression of METTL3 significantly upregulated PD-L1 in the A549 cell line, inhibiting the anti-tumor effects of T cells." (PMID 39720723, 2024). "Overall, the METTL3/PAX8/YTHDC1 axis has been revealed to play a pivotal role in repressing tumour occurrence, and is antagonized by miR-493-5p." (PMID 38993572, 2024). "METTL3 played a tumor-suppressive role in the RCC, and its downregulation was associated with larger tumor size, higher histological grade, and poor survival." (PMID 38503745, 2024). "In both in vitro and in vivo studies, the inhibition of METTL3 or IGF2BP3 was shown to enhance anti-tumor immunity through the PD-L1-mediated activation, depletion, and infiltration of T cells." (PMID 39759516, 2024). "Inhibition of tumor cell proliferation can be achieved by blocking METTL3, TRMT6/TRMT61A, the IGF2BP family, YTHDF2, or ALKBH5." (PMID 39372415, 2024). "METTL3 has been reported to be important in promoting tumorigenesis, accelerating the proliferation and metastasis of tumor cells, and promoting stem cell differentiation in a variety of cancers." (PMID 39678510, 2024). "Related to tumor heterogeneity or the different model systems used in the previous studies, METTL3 has oncogenic or tumor suppressor functions in different groups." (PMID 39497721, 2024). "The depletion of METTL3 in NK cells disrupts their homeostasis and hampers both their infiltration and function in the tumor microenvironment." (PMID 39686999, 2024). "In summary, this study has identified RNA methyltransferase METTL3 as a potential biomarker for ESCA detection, and its overexpression is associated with tumour development and progression." (PMID 38429907, 2024).
tumor (continued). "Clinical data demonstrate that METTL3 is upregulated in BC tissues, especially in phase T3-T4, or in patients with BC that are diagnosed with tumor metastasis in the lymphatic system." (PMID 38961497, 2024). "Our study lays both experimental and theoretical groundwork for a deeper understanding of the m6A methyltransferase complex and the development of targeted tumor therapies focusing on METTL3." (PMID 38965238, 2024). "The tumor volume exhibited a more rapid growth in the mice injected with METTL3-silenced GCSCs containing the methylated PSMA3-AS1 or MIR22HG than mice without the lncRNA methylation." (PMID 38600465, 2024). "The m6A modification of Jak1 mRNA in tumor-infiltrating myeloid cells (TIM) via METTL3 improves the translation efficiency of JAK1 protein and STAT3 phosphorylation." (PMID 39136000, 2024). "Inhibition of METTL3 enhanced anti-tumor immunity, T cell activation, exhaustion, and infiltration in vitro." (PMID 39720723, 2024). "Currently, studies have elucidated the role of METTL3 in promoting cell proliferation and angiogenesis, and its role in promoting tumor cell proliferation and angiogenesis has been confirmed through a series of experiments." (PMID 39295872, 2024). "METTL3 plays a crucial role in driving the progression of BCa by promoting angiogenesis around tumor cells." (PMID 39295872, 2024). "Overall, these studies illustrate the close connection between METTL3 and tumor angiogenesis, and demonstrate that METTL3 has potential as a target for cancer diagnosis and treatment." (PMID 39691597, 2024). "Our study positions METTL3 as an epigenetic checkpoint, highlighting the potential of targeting METTL3 to invigorate intrinsic anti‐tumour defenses and overcome immune resistance." (PMID 39568154, 2024). "METTL3 mediates the m6A methylation on mammalian RNAs and is crucial in influencing angiogenesis and promoting tumor progression." (PMID 39136000, 2024). "Compared to SKOV3 cell xenografts, xenografts with down-regulation of METTL3/14 showed an increase in tumor size after 27 g/kg of EZMLD treatment." (PMID 39103890, 2024). "Quantitative analysis demonstrated that NIS, PAX8, NKX2.1, TG, TPO and Hhex levels were significantly decreased upon METTL3 deletion, which suggests that METTL3 promotes TC dedifferentiation and performs a tumour suppressor role." (PMID 38993572, 2024). "Mechanistically, elevated transcription activity driven by the hypoxic tumor microenvironment is responsible for the aberrant expression of METTL3." (PMID 38233403, 2024). "METTL3 expression was found to be decreased in tumor-infiltrating NK cells, and its protein expression level was positively correlated with NK cell effector molecules." (PMID 39072324, 2024). "In liver cancer, METTL3 overexpression drives tumor growth by promoting the degradation of SOCS2 mRNA and upregulating SNAIL translation, leading to epithelial–mesenchymal transition (EMT) in cancer cells." (PMID 39445003, 2024). "Mechanistically, METTL3 induces expression of tumor-promoting gene PLOD2 dependent on its methylase activity." (PMID 38233403, 2024). "Firstly, the “double-edged sword” nature of METTL3 is evident from its involvement in both tumorigenesis and tumor suppression, depending on the tissue type and the specific oncogenic pathways active." (PMID 39416774, 2024). "In tumor-infiltrating myeloid cells, a potent accumulation of lactate occurs, leading to the upregulation of methyltransferase-like 3 (METTL3) through lactylation." (PMID 38218942, 2024). "The lactylation modification of H3K18 promotes the expression of METTL3 in tumor immune microenvironment cells, while also inducing lactylation of the zinc finger domain of METTL3." (PMID 39010066, 2024). "IGF2BP3, as the m6A reader, directly recognized and bound with the m6A site of HDGF mRNA stability mediated by elevated METTL3 expression, which are correlated with tumor angiogenesis and liver metastasis by maintaining HDGF mRNA stability." (PMID 39009956, 2024).